RIPK3 (receptor interacting serine/threonine kinase 3)
Diseases named in the same sentence as RIPK3 in open-access papers (continued):
Sharing a sentence is not in itself a finding about the gene and the disease.
type-1 diabetes (1 paper, 2022). "In a mouse model of STZ-induced type-1 diabetes, the levels of phosphorylated RIPK3 and MLKL protein were higher in diabetic hearts after 2 months of last STZ injection when compared to sham mice." (PMID 36030201, 2022). "Type 1 diabetes was induced in RIPK3 knockout, MLKL knockout and wild-type mice." (PMID 36030201, 2022).
Venous thrombosis (1 paper, 2020). Formation of a blood clot (thrombus) inside a vein, causing the obstruction of blood flow. "Those that have been performed, however, suggest an important role of the RIPK1/RIPK3/MLKL driven necroptosis pathway in venous thrombosis." (PMID 33142926, 2020). "Thus far, investigations into the role of RIPK3 in venous thrombosis have been limited." (PMID 33142926, 2020). "Given the ready availability of inhibitors of RIPK1/RIPK3 and the large clinical impact of venous thrombosis annually worldwide, the mechanistic relationship between RIPK1/RIPK3/MLKL, platelets, NETosis and venous thrombosis certainly merits further investigation." (PMID 33142926, 2020).
VEXAS syndrome (1 paper, 2024). An adult-onset inflammatory disease that affects only males and is caused by somatic, not germline, mutations. "Plasma levels of lactate dehydrogenase (LDH), a marker of necrosis and cellular injury, correlated with VEXAS syndrome, as well as RIPK1 and RIPK-3, a key kinase involved in programmed necroptosis and inflammatory cell death." (PMID 38291039, 2024).
tumor (259 papers, 2014 to 2026). "Of note, the indicated genetic deficiencies were only present in tumor cells while tumor-infiltrating immune or stroma cells in the TME were proficient for RIPK3 and MLKL in these experiments." (PMID 40345706, 2025). "Receptor-interacting serine/threonine-protein kinase 3 (RIPK3)-deficient TAMs enhance M2 polarization via fatty acid oxidation, whereas decitabine modulates metabolism to boost anti-tumor immunity." (PMID 40242773, 2025). "Receptor-interacting serine/threonine-protein kinase 3 (RIPK3) is deficient in tumor-infiltrating MDSCs, resulting in suppression of cholesterol synthesis." (PMID 40270603, 2025). "In colorectal cancer (CRC), RIPK3 deficiency correlates with increased N2-type tumor-associated macrophages (TAMs) and enhanced tumor aggressiveness." (PMID 41267084, 2025). "It was reported that the elimination of RIPK3 decreases the infiltration of MDSCs and tumor-associated macrophages (TAMs) and increases the proportions of lymphocytes, indicating an immune activated context." (PMID 40064873, 2025). "Concomitantly, ectopic activation of RIPK3 to promote tumor APC loading of tumor antigens is associated with enhanced CD8+ leukocyte-mediated anti-tumor responses." (PMID 38553639, 2024). "For instance, expression of RIPK3 and other necroptotic adapters in tumor cells was associated with improvement in CD8+ T cell infiltration in hepatocellular carcinoma, cholangiocarcinoma, and prostate cancer." (PMID 38858387, 2024). "The reduction in tumor nodules upon RIPK3 deletion was primarily associated with the stromal rather than the hematopoietic compartment, emphasizing the significance of the tumor microenvironment in cancer progression." (PMID 39209834, 2024). "In a B16-OVA tumor model and even a RIPK3-deficient CT26 tumor model, MLKL mRNA treatment induced necroptotic cell death and subsequent antitumor immunity." (PMID 38799433, 2024). "The increased expression of PPARγ in RIPK3-deficient mice has been shown to prevent tumor development." (PMID 38684668, 2024). "For instance, expression of RIPK3 and other necroptotic adaptors in tumor cells was associated with improvement in CD8+ T cell infiltration in hepatocellular carcinoma, cholangiocarcinoma, and prostate cancer." (PMID 38196632, 2023). "RIPK3, a central factor of necroptosis, coordinates fatty acid metabolism and hepatocarcinogenesis in tumor-associated macrophages, highlighting a potential strategy that can be used to target immunometabolism in HCC16." (PMID 37324188, 2023). "In human tumor cell lines, the necroptosis pathway is often inhibited due to the loss of RIPK3 expression." (PMID 36768641, 2023). "Up-regulation of RIPK3 expression can inhibit the immunosuppressive activity of tumor-associated macrophages to a certain extent, which can suppress HCC tumorigenesis." (PMID 37324188, 2023). "RIPK3 (necroptosis-related molecules) orchestrates the breakdown of fatty acids in tumor-associated macrophages and the development of hepatocarcinogenesis." (PMID 36267408, 2022). "Genetic evidence showed that RIPK3 deficiency leads to reduced endothelial cell permeability or necroptosis, thereby suppressing tumor metastasis." (PMID 35962126, 2022). "Deficiency of either RIPK3 or MLKL prevented development of skin inflammatory lesion in RIPK1E-KO mice." (PMID 36344541, 2022).
tumor (continued). "For instance, the key mediator of necroptotic pathway, RIPK3 is downregulated in several cancer types, which associates with the increased tumor aggressiveness and chemoresistance 9-11." (PMID 35165523, 2022). "RIPK3-deficient (Ripk3-/-) mice exhibit increased tumor formation in Apcmin/+ spontaneous intestinal tumorigenesis." (PMID 33996591, 2021). "The expression of RIPK3 has a significant positive association with the tumor-infiltrating immune cells populations in various tumor type, thereby activating anti-cancer responses." (PMID 34419074, 2021). "Association between AXL and RIPK3 immunoreactivity and clinical–pathological variables, sentinel lymph node status, and tumor-infiltrating lymphocytes (TILs) was assessed." (PMID 34745951, 2021). "They showed that high tumor expression of RIPK3 was associated with better DFS after adjuvant chemotherapy, thus a potentially useful predictive marker for the efficacy of adjuvant chemotherapy." (PMID 32742497, 2020). "For instance, in metastatic lung cancer, loss of RIPK3 was documented to reduce the number of tumor nodules by 38%." (PMID 32752206, 2020). "In order to understand the relevance of necroptosis in tumor growth and the in vivo kinetics of the RIPK3 expression loss during tumorigenesis, we evaluated the changes in RIPK3 mRNA levels in published transcriptomics datasets." (PMID 30157175, 2018). "This strategy enabled us to induce necroptotic cell death and subsequent antitumor immunity even in the context of the RIPK3-deficient CT26 tumor model." (PMID 30143632, 2018). "Here, we show that RIPK3 expression loss occurs progressively during tumor growth both in patient tumor biopsies and tumor xenograft models." (PMID 30157175, 2018). "Our results show that the reduced tumor nodule formation in RIPK3-deficient mice cannot be attributed to the failure to respond to one stimuli alone." (PMID 28151480, 2017). "Induction of necroptosis in tumor cells by triggering RIPK3 resulted in the release of damage-associated molecular pattern molecules, subsequent dendritic cell activation, and priming of tumor antigen-specific IFNγ-producing T cell." (PMID 29312298, 2017). "The loss of kinase activity of RIPK1 and the complete loss of RIPK3 were found to be important in the ability of the tumor cells to form lung nodules." (PMID 28151480, 2017). "Taken together, these results show that RIPK1 or RIPK3-deficient ECs fail to respond to tumor-induced vascular permeability or VEGF-A-induced permeability and angiogenesis, resulting in a defect in B16-F10 transendothelial migration." (PMID 28151480, 2017). "Bone marrow chimeras showed the involvement of the stromal but not the hematopoietic compartment was critical for the loss of tumor nodules in the lung in Ripk3−/− mice." (PMID 28151480, 2017). "After 14 dpi, tumor nodules in the mice with RIPK3-deficient hematopoietic compartment were similar in number compared with mice with wild-type hematopoietic compartment." (PMID 28151480, 2017). "We then found the ability of tumor cells to transmigrate through Ripk3−/− endothelial barrier to be deficient and that cell death in the EC layer was independent of the genotype when tumor cells were co-incubated." (PMID 28151480, 2017). "In summary, these results suggest expression of RIPK3 as a primary determinant for resistance or susceptibility of the analyzed tumor cells, but also point to secondary factors that additionally confer resistance independent from RIPK3." (PMID 24507727, 2014). "In addition, necroptosis involving RIPK1 and RIPK3 causes tumor cell death and modulation of immune responses in the tumor microenvironment (TME)." (PMID 40257494, 2025). "Interestingly, necroptosis has also been implicated in anti-tumor immunity, with research suggesting that RIPK3 plays a regulatory role in the activity of natural killer T (NKT) cells, enhancing NKT-mediated anti-tumor responses." (PMID 39949740, 2025).
tumor (continued). "Moreover, the increased polarization of macrophages toward the M1 phenotype in the TME following RIPK3 activation suggests a decrease in antiinflammatory factors, which are often associated with tumor progression and immunosuppression." (PMID 39560995, 2024). "Since RIPK3 can also promote apoptosis and NF-κB-dependent inflammation, it remains difficult to determine the contribution of necroptosis-associated release of damage-associated molecular patterns (DAMPs) in anti-tumor immunity." (PMID 38196632, 2023). "Furthermore, RIPK3 deletion diminishes the infiltration of immunosuppressive myeloid cell subsets (tumor-associated MΦs (TAMs), myeloid-derived suppressor cells (MDSCs) and DCs), and the proportions of T cells and B cells are increased." (PMID 36482419, 2022). "Necroptosis‐independent functions of RIPK3 may be driving its loss in cancer by providing accretion of tumor progression in concert with increased oncogenic signaling such as ERK." (PMID 36161785, 2022). "Since we observed that tumor formation spontaneously increased in an age‐dependent manner in Ripk3−/‐ mice, we wished to examine whether RIPK3 deficiency promotes susceptibility to tumor progression triggered by carcinogens at a relatively young age." (PMID 36161785, 2022). "Bioinformatics analysis of the TCGA database strongly supports these in vitro results, as it showed that the expression of RIPK3 has a significant positive association with the tumor-infiltrating populations of several types of CD8+ T cells or DCs in various tumor type." (PMID 34419074, 2021). "Since loss of RIPK3 resulted in higher tumor burdens in the Apcmin/+ model, we hypothesized that RIPK3 inhibited tumor progression through regulating cellular proliferation." (PMID 33996591, 2021). "Furthermore, genetic evidence showed that RIPK3 deficiency leads to reduced endothelial cell permeability or necroptosis, thereby suppressing tumor metastasis." (PMID 32332696, 2020). "Furthermore, loss of RIPK3 or chemical inhibition of necroptosis significantly reduced tumorigenesis in their tumour model." (PMID 31416294, 2019). "For example, loss of RIPK3 in tumors would result in decreased cross-priming and increased escape from immunity, thus benefiting tumor survival and growth, but inadvertently it would also result in loss of necroptosis potential because of the essentiality of RIPK3 for necroptosis." (PMID 30157175, 2018). "Loss of RIPK3 in the tumor microenvironment reduced the number of tumor nodules in the lung by 46%." (PMID 28151480, 2017). "However, the loss of kinase activity in RIPK3 or the loss of MLKL only marginally altered the ability of tumor cells to form in the lung." (PMID 28151480, 2017). "Interestingly, the direct intratumoral induction of necroptosis using an AAV vector encoding for a constitutively active form of RIPK3 induce necroptosis in a part of the tumor cells, improves tumor immunogenicity, and synergizes with immune checkpoint blockade to promote a durable tumor clearance." (PMID 34490126, 2021). "Hence, our findings suggest that RIPK3 loss may be dependent on a tumor cell–intrinsic mechanism in vivo or due to interactions with stromal or innate immune cells." (PMID 30157175, 2018). "While one report proposed that RIPK3 expression is suppressed in cancer cells by promoter methylation, it is more likely that in solid tumors RIPK3 expression is inhibited by hypoxia, which has been implicated in promoting cell survival and angiogenesis during tumor progression." (PMID 27344176, 2016). "Knocking out Irf3, Irf7, Gsdme or Ripk3 in B16F10 tumor cells each reduced DAC’s effectiveness at inducing immune control of the tumor, which indicates that the derepression of multiple innate immune pathways helped to restore immune control." (PMID 41315764, 2026). "Intra-tumoral activation of RIPK3, a key component of the necroptotic pathway, has been demonstrated to enhance anti-tumor immunity and promote tumor regression." (PMID 39865281, 2025).
tumor (continued). "Our findings that ICI immunotherapy relies on tumor cell-intrinsic RIPK3/MLKL signaling are in line with previous reports demonstrating that artificial activation of the necroptosis pathway can boost ICI antitumor efficacy." (PMID 40345706, 2025). "This pro-carcinogenic role of RIPK3 was attributed to a necroptosis-independent function that elicited macrophage-induced anti-tumor immune suppression through CXCL1/Mincled signaling." (PMID 39971907, 2025). "In pancreatic cancer, elevated RIPK1 and RIPK3 levels enhance tumor migration and invasion, while low MLKL expression is associated with worse outcomes." (PMID 40969770, 2025). "Although RIPK3 is silenced in several tumor types via promoter hypermethylation, it remains expressed and functional in others, making necroptosis a viable target in specific contexts." (PMID 41354733, 2025). "The RIPK1/RIPK3/MLKL signaling cascade constitutes a central axis governing necroptotic cell death in tumor biology." (PMID 41180485, 2025). "Necroptosis is a highly inflammatory form of regulated cell death driven by Receptor-Interacting Protein Kinase 3 (RIPK3), which plays a crucial role in immune responses, inflammatory diseases, and tumor microenvironment modulation." (PMID 41354733, 2025). "The concurrent activation of ferroptosis and RIPK3‐mediated necroptosis through Mn2+‐induced ROS and RIPK3 expression creates a potent synergistic effect that not only enhances tumor cell killing but also reorganizes the tumor immune microenvironment." (PMID 40755438, 2025). "The mRNA levels of RIPK3 displayed an expression trend opposite to that of SPOP across the tumor cell lines." (PMID 41122967, 2025). "Transfection of RIPK3 into tumor cells can induce necroptosis, which can be synergized with immunotherapy to maintain an activated immune response." (PMID 40064873, 2025). "Treatment of mice with a RIPK1 inhibitor or endothelial cell-specific deletion of RIPK3 significantly reduced tumour cell-induced endothelial necroptosis, tumour cell extravasation, and metastasis." (PMID 41334873, 2025). "For instance, in pancreatic ductal adenocarcinoma, elevated levels of RIPK1, RIPK3, and MLKL are associated with accelerated tumor progression." (PMID 39949740, 2025). "In contrary, RIPK3 deletion in macrophage force the M2 phenotype (anti-inflammation) polarization, which further facilitate tumor progression." (PMID 40064873, 2025). "Although TSZ treatment markedly increased the phosphorylation level of RIPK3, the basal expression level of RIPK3 in tumor cell lines was extremely low." (PMID 41122967, 2025). "Injection of genetically engineered tumor cells expressing a constitutively active form of RIPK3 synergized with ICI immunotherapy for durable tumor clearance in mice." (PMID 40345706, 2025). "By contrast, recurrent BC epigenetically reactivate RIPK3 to drive proliferation and sustain tumor fitness via pathways including YAP/TAZ activation." (PMID 41267084, 2025). "Taken together, these data demonstrate that tumor cells undergoing RIPK3/MLKL-mediated necroptotic cell death can induce uptake of tumor debris by and maturation of bystander APCs." (PMID 40345706, 2025). "In some cancers, RIPK3 levels are elevated during early disease stages and inversely correlated with tumor burden and biomarkers of malignancy, suggesting a tumor‐suppressive role in the initial phases of oncogenesis." (PMID 40900810, 2025). "CRISPR-based mechanistic studies of necrosome components RIPK3 and MLKL in T-cell lymphoma models demonstrate that loss of these proteins substantially impairs tumor cell response to toltrazuril." (PMID 41267084, 2025). "SPOP and RIPK1 were substantially overexpressed in tumor tissues, while RIPK3 expression was reduced." (PMID 41122967, 2025).